ENO1 (enolase 1)
Diseases named in the same sentence as ENO1 in open-access papers (continued):
Sharing a sentence is not in itself a finding about the gene and the disease.
pancreatic ductal adenocarcinoma (13 papers, 2017 to 2025). An infiltrating adenocarcinoma that arises from the epithelial cells of the pancreas. "Yin and his colleagues detected ENO1 overexpression in pancreatic ductal adenocarcinomas (PDAC) patients, and it was positively associated with metastasis of lymph node, clinical stage, and poor prognosis." (PMID 35805203, 2022). "Due to its tumor-related overexpression and ability to induce humoral and/or cellular immune responses, ENO1 has already been classified as a tumor-associated Ag in solid cancers, such as pancreatic ductal adenocarcinoma (PDA)." (PMID 27906678, 2017). "In pancreatic ductal adenocarcinoma-bearing mice, a mAb targeting pancreatic ductal adenocarcinoma-associated antigen α-enolase (ENO1) inhibited in vivo infiltration of MDSCs into the tumor microenvironment and attenuated their restraint of the effector T cell response." (PMID 30792719, 2019). "A study on pancreatic ductal adenocarcinoma (PDAC) found that ENO1 mediates cell apoptosis by regulating ERK activation." (PMID 40941354, 2025). "in 2020 have examined Enolase 1 (ENO1)‐targeted SPIONs using the ENO1 antibody to evaluate pancreatic ductal adenocarcinomas (PDACs), which are the deadliest cancer with a 5‐year survival rate of 5% for all stages." (PMID 34694670, 2021). "The correspondence between peripheral and intratumoral ENO1-specific immune responses has been demonstrated, and the circulating ENO1-specific T cells exhibited an effective anticancer effect in pancreatic ductal adenocarcinoma." (PMID 33643901, 2020). "Interestingly, ENO1-knockout could inhibit cell invasion and migration and prevent cell proliferation in pancreatic ductal adenocarcinoma (PDAC) cells (PANC-1 and MIA PaCa-2); meanwhile, tumor cell glucose uptake and lactate excretion also decreased significantly." (PMID 36845730, 2023).
autoimmune disease (12 papers, 2012 to 2025). A disorder resulting from loss of function or tissue destruction of an organ or multiple organs, arising from humoral or cellular immune responses of the individual to their own tissue constituents. "Zooming on the nervous systems, positive anti-ENO1 Ab were demonstrated in autoimmune diseases associated with CNS impairment, such as lymphocytic hypophysitis and Hashimoto's encephalopathy." (PMID 34189450, 2021). "Additionally, aberrant ENO1 expression or function is closely associated with autoimmune diseases, cardiovascular diseases, and neurological disorders." (PMID 40859388, 2025). "Multiple factors, mechanisms, pathways, co-morbidities and clinical presentations are shared between ENO1 and its corresponding AAE Ab and CD or with CD-associated autoimmune diseases." (PMID 34189450, 2021). "Antibodies to ENO1 have been reported in a variety of infectious and autoimmune diseases, including RA." (PMID 30001173, 2018). "Autoantibodies against alpha-enolase (ENO1) are often detected in various infectious and autoimmune diseases." (PMID 30001173, 2018). "In addition to their conventional roles inside of cells, ENO-1 and cofilin-1 can be found on cell surfaces and are also involved in autoimmune diseases." (PMID 38618493, 2023). "Since ENO1 antibodies have been proposed as a drug in cancers and autoimmune diseases, in regard to EV-A71 antiviral therapy, ENO1 targeting might be a therapeutic strategy for preventing severe disease of EV-A71 infection." (PMID 35130884, 2022). "Besides, ENO1 autoantibodies were found to exist in several diseases including autoimmune diseases and viral infections." (PMID 35130884, 2022). "Given that IL17A‐targeted monoclonal antibodies (e.g., secukinumab) are already FDA‐approved for autoimmune diseases with well‐characterised safety profiles, combining such agents with neoantigen or ENO1 vaccines could be rapidly tested in early‐phase PDA trials." (PMID 40831074, 2025). "Interestingly, data indicate that ENO1 acts as an autoantigen in several autoimmune diseases." (PMID 30863411, 2019).
breast tumor (12 papers, 2007 to 2026). "C3 was from the breast tumor with the expression of ENO1 (stress response associated gene), whereas C6 was from both tumor and NAT samples of a variety of tumors." (PMID 38010945, 2024). "An unpaired t-test revealed a significant difference between benign and malignant tumors (p=0.0035 and CI=-56.44 to -9.409), indicating that the intensity of ENO1 immunohistochemical staining is directly related to the type of breast tumor." (PMID 41179678, 2025). "In this study, we investigated ENO1 expression in benign and malignant breast tumors using immunohistochemistry, analyzing both the tissue distribution pattern and staining intensity." (PMID 41179678, 2025). "Further studies of ENO1 must be conducted to confirm its role in cancer, more specifically, in breast tumors." (PMID 41179678, 2025). "Consistent and complementary to differential gene expression in HER2+ BCBM versus matched primary breast tumor, one module (module_1) was brain-specific and enriched for ENO1-mediated metabolic reprogramming and mTORc related signaling." (PMID 35082299, 2022). "The ENO1/MBP-1 ratio influences cancer aggressiveness, as demonstrated in human breast tumors where overexpression of ENO1 and extracellular matrix metalloproteinases MMP-2 and MMP-9, concomitant with MBP-1 downregulation, correlates with worse prognosis." (PMID 33584813, 2020). "Overexpression of the TPI, PGK1 and ENO1 enzymes has been demonstrated in a series of breast tumors." (PMID 28430808, 2017). "In the present study, by using highly specific monoclonal antibodies to α-enolase, we confirm that ENO1 is significantly overexpressed in primary breast tumor specimens." (PMID 20886042, 2010). "Three enzymes of the 187 gene profile, TPI, PGK1, and ENO1, which are involved in the glycolytic pathway, were also found to be significantly overexpressed in the HER-2/neu-positive breast tumors." (PMID 17989776, 2007). "The intensity of immunohistochemical staining of Enolase-1 (ENO1) observed in malignant tumors, especially in cases of unfavorable outcome (death), suggests a direct relationship between the expression of this enzyme and the malignancy of breast tumors." (PMID 41179678, 2025). "In addition, we used the in breast tumor and normal tissue derived from LTF, LCP1, AZU1, and ENO1 differences in total protein expression data analysis." (PMID 37304069, 2023).
cholangiocarcinoma (11 papers, 2014 to 2025). A carcinoma that arises from the intrahepatic biliary tree (intrahepatic cholangiocarcinoma) or from the junction, or adjacent to the junction, of the right and left hepatic ducts (hilar cholangiocarcinoma). "In cholangiocarcinoma, USP21 enhances the protein stability of HSP90 and ENO1 by removing their K48-linked ubiquitin chains." (PMID 41301681, 2025). "ENO1 was highly expressed in the tumor tissues of patients with cholangiocarcinoma, which was positively correlated with peritoneal lymph node metastasis and prognosis." (PMID 29483925, 2018). "Targeting the USP21/HSP90/HIF1α and USP21/ENO1 signaling axes may provide a rational basis for precision therapies and improved prognostication in cholangiocarcinoma." (PMID 41301681, 2025).
cervical carcinoma (9 papers, 2011 to 2023). A carcinoma arising from either the exocervical squamous epithelium or the endocervical glandular epithelium. "SLC25A5 and ENO1, which we found in our common core, were recently identified among six hub genes prognostic for cervical cancer." (PMID 36996232, 2023). "The ENO1 regulator gene, which we found to be overexpressed in cervical cancer, positively correlated with PD-L1 (CD274) and TGFB1 in both data sets, providing further indication for immunotherapy targeting in this malignancy." (PMID 28670312, 2017). "Interestingly, monoclonal antibody directed against ENO1 inhibited invasion, proliferation, and clone formation of cervical cancer cells, suggesting that ENO1mAb triggers promising anti-tumor effects." (PMID 35204345, 2022). "Similarly, studies have shown that ENO1 monoclonal antibody plays a certain role in inhibiting the proliferation and invasion of cervical cancer cells." (PMID 36620599, 2022). "The Human Protein Atlas also shows medium ENO1 expression in cervical cancer." (PMID 28670312, 2017). "Also, IPA diseases analysis data showed 8 proteins were associated with cervical cancer, including ANX1, ANX2, ANX 5, ENO1, HSP90AB1, YWHAE, TFRC, HSP90, and KRT19." (PMID 23243437, 2012). "We found that HPV E6/E7-related master regulators (ENO1, FOSB, PA2G4, SOX9, TEAD4, FOXO4, and MNT) were significantly differently expressed (p < 0.001) in the cervical cancer TCGA samples (n = 306) than in normal cervix (n = 11) tissue." (PMID 28670312, 2017). "Based on our results and these previous studies on the role of ENO1 in tumor progression and immune response, we propose that targeting ENO1/ENOA in cervical cancer will provide an additional therapeutic benefit and increase the patient survival." (PMID 28670312, 2017). "The following genes ENO1, FOSB, PA2G4, SOX9, and TEAD4 were highly expressed in cervical cancer in comparison to normal cervix (p < 0.001), while FOXO4 and MNT were significantly lower in cervical cancer (p < 0.001)." (PMID 28670312, 2017). "In the Human Protein Atlas, OVOL1 and PRDM1 showed low, ENO1 medium, while ZNF365 showed no protein expression in cervical cancer." (PMID 28670312, 2017).
endometriosis (9 papers, 2011 to 2024). The growth of functional endometrial tissue in anatomic sites outside the uterine body. "According to reports, ENO1 is an important biomarker for the development and prognosis of endometriosis." (PMID 38585644, 2024). "To further validate the interaction between KAT2A and ENO1 in endometriosis progression, we transfected ESCs with sh-KAT2A and ENO1 overexpressing plasmid and tested the biological functions of ESCs." (PMID 38585644, 2024). "Research has shown that ENO1 performs higher in patients with endometriosis and is currently the most promising target drug in clinical practice." (PMID 38585644, 2024). "In summary, we found that succinylation of ENO1 mediated by KAT2A played a role in promoting the progression of endometriosis." (PMID 38585644, 2024). "For diagnosing endometriosis, previous research discovered two potentially useful urinary biomarkers, Enolase-1 and vitamin D-binding protein (VDBP)." (PMID 35453583, 2022). "Another two linear regions of ENO1, aa53–87 and aa207–238, were specifically recognized by ENO1Abs from endometriosis patients." (PMID 35707546, 2022). "Urinary biomarkers of endometriosis, including Enolase-1 and urinary vitamin D binding protein (VDBP), have previously been reported." (PMID 35453583, 2022). "As a secondary outcome, we noted that patients with endometriosis had significantly higher enolase-1 and enolase/Cr levels in the luteal phase than in the follicular phase." (PMID 33062681, 2020). "In line with our findings, some studies have reported elevated serum levels of CA125, CA19-9, and enolase-1 in women with endometriosis." (PMID 33062681, 2020). "In Yun and coworkers' study, the sensitivity of normalized urine enolase-1 (enolase/Cr) was 76.9% for the diagnosis of endometriosis." (PMID 33062681, 2020). "Over-expression of ENO1 and HIF1α in CCOC also demonstrates a clinical link to CCOC's association with endometriosis." (PMID 21754983, 2011). "It has been suggested that ENO1 could be a useful clinical marker for the diagnosis of endometriosis." (PMID 38585644, 2024). "ENO1 autoantibody is a new serum indicator for endometriosis." (PMID 38585644, 2024). "In our study, no obvious significant differences could be detected between urine enolase-1 or the urine enolase-1-creatinine ratio between patients with endometriosis and normal controls." (PMID 35453583, 2022). "Despite elevation in women with endometriosis, enolase-1 lacked sufficient diagnostic power as an individual analyte (sensitivity 56% and specificity 72%) in a separate study." (PMID 26240814, 2015). "Therefore, controlling the expression of ENO1 may be an effective tool for treating patients with endometriosis." (PMID 38585644, 2024). "Therefore, in this study, we first examined the gene content of succinylation in ectopic patients with uterine fibroids (EN) and ectopic endometrial (EC) and further tested whether it could modulate ENO1 in the treatment of endometriosis." (PMID 38585644, 2024). "Therefore, ENO1 targeting is crucial for exploring treatment methods for endometriosis." (PMID 38585644, 2024). "Therefore, we further tested whether KAT2A was involved in the regulation of ENO1 to reveal its biological mechanism in the development of endometriosis." (PMID 38585644, 2024). "Although multiple amino acid segments of ENO1 were found to be potentially specific epitopes to RA, cancer-associated retinopathy, lupus nephritis, and endometriosis, there is still a lack of systemic investigation into disease-specific ENO1 epitopes, and there are no reports on miscarriage." (PMID 36674531, 2023). "The present study revealed that concurrent measurement of enolase-1, CA125, and CA19-9 might be a valuable noninvasive test for the identification of endometriosis." (PMID 33062681, 2020). "However, no studies are showing that modulation of succinylation of ENO1 and thus regulation of endometriosis." (PMID 38585644, 2024).
endometriosis (continued). "However, there is no research confirming whether KAT2A can regulate ENO1 and reduce the condition of patients with endometriosis." (PMID 38585644, 2024). "Although urinary enolase 1, enolase/Cr, CA 125, and CA19-9 levels are increased in women with endometriosis, these parameters alone are reported to possess no diagnostic power." (PMID 33062681, 2020).
candidiasis (8 papers, 2014 to 2025). Infection with the organism Candida. "Alpha–enolase (Eno1) is a multifunctional protein and represents an important marker for invasive candidiasis." (PMID 32326294, 2020). "Eno1 was responsible for transglutaminase activity on cell wall of C. albicans and acts as the major antigen in patients with candidiasis." (PMID 33115324, 2020). "The property of Eno1 as the foremost antigen in patients with candidiasis is well known." (PMID 40586608, 2025). "Eno1 is currently considered a moonlighting protein, a glycolysis and gluconeogenesis enzyme that can be secreted to the cell wall of Candida spp. and is well known for promoting a strong humoral immune response in patients with invasive candidiasis." (PMID 38324097, 2024). "C. albicans cell surface located Eno1 has been identified as a moon-lighting protein with unrelated glycolytic enzyme function such as transglutaminase activity and major antigen in patients with candidiasis." (PMID 33115324, 2020). "Another point to consider with reference to invasive candidiasis is the development of vaccines, and immunization trials in animal models have been conducted with encouraging success rates using various C. albicans components such as heat shock protein 90 (Hsp90), Hwp1-N, Eno1 and Met6 among others." (PMID 38324097, 2024). "In a C. albicans study, the detection of the antibody-reactivity patterns between the fungal Eno1 and Pgk1 proteins and the sera from patients with a Candida infection could differentiate patients with invasive candidiasis from those with non-invasive candidiasis." (PMID 38542504, 2024). "The predicted interaction partner on the pathogen side, ENO1, is not only a key component of glycolysis, but is also an immunodominant antigen circulating in the bloodstream of patients with disseminated Candida infections and a highly immunogenic protein in Candida-infected mice." (PMID 26300851, 2015). "In contrast, in non-neutropenic patients, invasive candidiasis could be predicted by measuring their serum antibody signature against the C. albicans proteins Hsp90 and Eno1 prospectively." (PMID 26909070, 2016).
COVID-19 (8 papers, 2021 to 2025). A disease caused by infection with severe acute respiratory syndrome coronavirus 2. "On the other hand, an inflammation-associated protein, ENO1, was down-regulated in COVID-19-children against COVID-19-adults, indicating that anti-inflammatory processes were also actively triggered in the proteomic level." (PMID 34335977, 2021). "Age and inflammation (IL-6, a marker of COVID-19 severity), as well as glycolytic enzymes (enolase–ENO1), also ranked amongst the top correlates to d-dimer measurements." (PMID 38543504, 2024). "Among them, six genes (CXCR4, ENO1, FASN, GATA6, PDK1 and TUBB3) have been reported to be associated with the pathological mechanism of COVID-19 and OA." (PMID 37291167, 2023). "Interestingly, ENO1, a key enzyme in the last steps of the catabolic glycolytic pathway, was significantly downregulated in COVID-19-children." (PMID 34335977, 2021). "In the COVID-19 dataset, CXCR4 (AUC:0.733), ENO1 (AUC:0.809), FASN (AUC:0.830), HIST1H4I (AUC:0.755), HIST1H4K (AUC:0.743), TUBA4A (AUC:0.811) and TUBB3 (AUC:0.814) exhibited relatively good diagnostic efficiency for distinguishing the patients with COVID-19 from healthy controls." (PMID 37291167, 2023). "The only pathway that was significantly downregulated in COVID-19 monocytes was glycolysis, with decreased expression of a number of enzymes involved in glucose degradation, including PFKP, ENO1, PFKB4 and others." (PMID 36572683, 2022). "ENO1 and TUBB3 were found to be probably related to the progression of OA, while FASN and GATA6 may participate in COVID-19." (PMID 37291167, 2023).